MMP9 (matrix metallopeptidase 9)
Diseases named in the same sentence as MMP9 in open-access papers (continued):
Sharing a sentence is not in itself a finding about the gene and the disease.
colorectal cancer (continued). "In this study, colorectal cancer stem cell-derived exosomes promoted BCL-2, MMP-9 and Vimentin expressions, but inhibited those of E-cadherin, Bax and cleaved caspase-3." (PMID 35470736, 2022). "According to the findings obtained from combined treatment of resveratrol and 5-FU, it was found that resveratrol reduces phosphorylated NF‐κB, IκBα, and IKK levels as well as MMP-9, COX-2, IL-6, and TNF-α levels in colorectal cancer cells." (PMID 35366874, 2022). "The Sparreboom's prediction model was first validated, which showed that for patients with colorectal cancer, serum CRP, and peritoneal MMP9 is also reliable for diagnosing AL on POD3." (PMID 35657137, 2022). "PIGF/Flt-1 signalling is integral in colorectal cancer progression through increasing the phosphorylation of p38 MAPK, thereby upregulating MMP9 expression; resulting in increasing cellular migration/invasion." (PMID 35154142, 2022). "Using colorectal cancer cell lines and zebrafish xenotransplant models, we found that deflamin exhibits anti-MMP-2 and anti-MMP-9 activity, being able to reduce tumor size and metastasis formation in vivo." (PMID 36551666, 2022). "The increased expression of N-cadherin can also promote both proliferation and migration of colorectal cancer cells by EMT induction, as confirmed by the enhancement of the MMP9 level in the present study." (PMID 34094030, 2021). "NK cells from colorectal cancer patients are polarized toward a pro-angiogenic phenotype, and they express angiogenin, MMP2 and MMP9." (PMID 34638439, 2021). "Some studies have found that Akt1 signaling significantly suppresses the expression of MMP2, MMP9, HIF1α, and VEGF in colorectal carcinoma cells." (PMID 34394377, 2021). "In colorectal cancer, CTHRC1 can enhance Erk phosphorylation, up-regulate MMP-9 expression, and promote extracellular matrix degradation, thereby promoting tumor cell invasion." (PMID 32156314, 2020). "Secretion of MMP9 (matrix metalloproteinase 9) from infiltrating neutrophils activates latent TGF-β and induces T cell suppression and tumor growth in a colorectal cancer model." (PMID 32849639, 2020). "At present, there are few studies about the functions of IL-17, MMP-9 and CD23 in colorectal cancer at home and abroad, so it is hard to cite a number of other experiment results to carry out comparison and discussion." (PMID 32461933, 2020). "For example, the mechanism of IL-17, MMP-9 and CD23 in colorectal cancer needs to be further investigated to verify our results." (PMID 32461933, 2020). "We aimed to detect IL-17, MMP-9 and CD23 in serum of patients with colorectal cancer to provide some proper references for diagnosis and treatment of this disease." (PMID 32461933, 2020). "IL-17, MMP-9 and CD23 were negatively correlated with treatment time, suggesting that the recovery of patients with colorectal cancer can be estimated by detecting the concentrations of IL-17, MMP-9 and CD23 in peripheral blood of patients." (PMID 32461933, 2020). "This study analyzed the correlation between the three and colorectal cancer as well as the relationship between the three and clinicopathology to verify the functions of IL-17, MMP-9 and CD23 in colorectal cancer." (PMID 32461933, 2020). "Rosmarinic acid inhibited colon cancer invasion and colorectal cancer metastasis by inhibiting MMP-2 and MMP-9 activity." (PMID 32102512, 2020). "Upregulation of miR-9 produces downregulation of TM4SF1, MMP2, MMP9 and VEGF in colorectal carcinoma, inhibiting cell migration and invasion." (PMID 32000679, 2020). "Overexpression of KiSS-1 reduces the invasiveness of colorectal cancer cells by blocking the PI3K/AKT/NF-κB pathway and inhibiting the expression of MMP-9 protein." (PMID 31783709, 2019). "Curcumin has been reported as an inhibitor of colorectal cancer invasion by means of AMPK-induced inhibition of NF-κB, urokinase-type plasminogen activator (uPA) activator, and matrix metalloproteinase-9 (MMP9)." (PMID 31590362, 2019).
colorectal cancer (continued). "Via regulating miR-182 and MMP9, β-catenin also altered cell invasion ability in HCT116 human colorectal carcinoma cells." (PMID 31772658, 2019). "Two monoclonal anti-MMP-9 antibodies, AB0041 and AB0046, were shown to inhibit tumor growth and metastasis in a model of colorectal carcinoma." (PMID 31461880, 2019). "The aim of our study was to investigate the prognostic roles of MMP-8, MMP-9, and TIMP-1 in colorectal cancer." (PMID 29929486, 2018). "MMP-9 and CRP serum levels have a significant predictive value in the assessment stage II to IV colorectal cancer which points to persisting inflammation-related process and its importance in the colorectal tumor genesis." (PMID 30154846, 2018). "Of median MMP-8, MMP-9, and TIMP-1 serum levels prior to surgery for colorectal cancer and for controls with benign disease, only TIMP-1 levels were higher in patients with CRC than in controls (P = 0.037, Mann-Whitney U-test)." (PMID 29929486, 2018). "MMP-9 is one of the key proteolytic enzymes in the breakdown and reconstruction of ECM in colorectal cancer (CRC) invasion and metastasis." (PMID 29520667, 2018). "MMP-9 has been implicated in the pathogenesis of several diseases including TB, and selective inhibition of MMP-9 (using AB0046) was efficacious in preclinical models of ulcerative colitis and colorectal cancer." (PMID 29758082, 2018). "In colorectal cancer HT-29 cells, treatment with gefitinib reduced the expression of MMP-2, MMP-9, and VEGF-A, which are involved in cancer cell invasiveness." (PMID 30187356, 2018). "We randomly chose 87 colorectal cancer tissue samples to analyze the expression levels of B7-H3, MMP2 and MMP9 by immunohistochemistry." (PMID 27145365, 2016). "Inhibition of PARP with 5-AIQ down regulates the expression of MMP-9 and MMP-2 as well as their activities via decreasing NF-kB expression, facilitating the suppression of tumor metastasis in colorectal cancer." (PMID 27659937, 2016). "In our study, we revealed that both MMP-9 and MMP-2 were co-expressed with B7-H3 in colorectal cancer tissue; the correlation coefficients were 0.7492 and 0.5643, respectively." (PMID 27145365, 2016). "In colorectal cancer and Lewis lung carcinoma (LLC), MDSCs promote angiogenesis through the production of matrix metalloproteinase 9 (MMP-9) and by the acquisition of endothelial cell properties in the tumor microenvironment." (PMID 27177328, 2016). "With the increase in pathological grading, staining intensities of LCN-2 and MMP-9 in neoplastic cells became stronger, and in high-grade intraepithelial LSTs expression was greater than in TNM stage I colorectal carcinomas." (PMID 27339395, 2016). "Matrix metalloproteinase-9 (MMP-9) is related to tumour development and progression in colorectal cancer (CRC) and its utility as biomarker has been suggested." (PMID 26264519, 2015). "Expression of matrix metalloproteinase 9 (MMP9) is elevated in a variety of inflammatory and oncology indications, including ulcerative colitis and colorectal cancer." (PMID 25961845, 2015). "NF-kappaB was also considered as one of the major contributors in the oncogenesis of chronic inflammation-induced colorectal carcinomas, most likely through the upregulation of its pro-survival target genes including cyclin D1, VEGF, IL-8, COX2, and MMP9." (PMID 24571667, 2014). "In many malignancies, including colorectal cancers, MMP7 and MMP9 are overexpressed and play a role in cancer progression by enhancing metastatic potential and tumor invasion." (PMID 23724058, 2013). "PlGF increased the invasion/migration ability of colorectal cancer cells by increasing the phosphorylation of p38 MAPK and upregulating MMP9 expression." (PMID 23799978, 2013). "In our previous study, we demonstrated that NCTD inhibited pulmonary metastasis of colorectal cancer CT26 cells in vivo and cell invasion ability in vitro, accompanied by the downregulation of MMP-9." (PMID 22615870, 2012).
colorectal cancer (continued). "A recent study verified altered levels of MMP-9 and VEGF-A in patients with early-stage breast and colorectal cancer when compared to normal patients." (PMID 20445741, 2010). "Matrix metalloproteinase-2 (MMP-2), matrix metalloproteinase-9 (MMP-9), and urokinase-type plasminogen activator (uPA) are involved in colorectal cancer invasion and metastasis." (PMID 16916471, 2006). "The purpose of this study was to determine the expression and cellular localisation of the 92 kDa type IV collagenase (MMP-9) protein and mRNA in human colorectal cancer (CRC)." (PMID 8883399, 1996). "Our data demonstrate a distinct pattern of MMP-9 and TIMP-1 mRNA expression in colorectal cancer and liver metastases suggesting distinct cellular origins as well as separate patterns of regulation." (PMID 7669564, 1995). "In the present study, we compare the topographical pattern of MMP-9 and TIMP-1 expression in colorectal cancer and liver metastasis by in situ hybridisation." (PMID 7669564, 1995). "SMAD4 deletion promotes colorectal cancer (CRC) expression of C-C Motif Chemokine Ligand 15 (CCL15) and recruits the CCR1 TAN (CCL15-CCR1 axis) with arginase-1 (ARG-1) and matrix metalloproteinase 9 (MMP-9) activities, thereby forming a pre-metastatic niche for disseminated tumor cells (e." (PMID 40160822, 2025). "Additionally, it has been reported that MMP9 plays a critical role in linking CRC with neuropathic conditions, potentially driving neuronal damage in colorectal cancer patients." (PMID 41009970, 2025). "Notably, MMP9 is overexpressed in a range of malignancies, such as NSCLC, colorectal cancer, and glioblastoma, facilitating tumor cell metastasis." (PMID 39440769, 2025). "As colorectal cancer progression involves the activity of MMP-2 and MMP-9, we investigated whether treatment with aronia extracts could affect gelatinase activity in SW-480 and HT-29 cells." (PMID 39683504, 2024). "Higher MMP-9 serum levels have been related to Crohn’s disease relapses, while elevated plasma levels of MMP-2, -9 and -13 have been addressed as potential biomarkers of colorectal cancer." (PMID 38802341, 2024). "The ability of curcumin to augment the antitumor effect of capecitabine in human colorectal cancer by modulating cyclin D1, COX-2, matrix metallopeptidase 9 (MMP-9), VEGF and C-X-C chemokine receptor type 4 (CXCR4), has been assessed by using an orthotopic mouse model." (PMID 37376060, 2023). "Two other anti-MMP9 monoclonal antibodies, B0041, which targets human MMP9, and B0046, which inhibits stroma-derived mouse MMP9, were found to be highly effective in a HCT 116 mouse colorectal cancer (CC) xenograft model." (PMID 35406619, 2022). "In colorectal cancer, AGP abrogates TLR4/NFκB/MMP-9 signaling pathway." (PMID 34795581, 2021). "The concentrations of IL-17, MMP-9 and CD23 obviously increased in peripheral blood of patients with colorectal cancer, the three were negatively correlated with treatment time and were significantly correlated with TNM staging and differentiation degree of colorectal cancer." (PMID 32461933, 2020). "However, IL-17, MMP-9 and CD23 in serum of patients with colorectal cancer were detected by experiments in this paper to provide some proper references for diagnosis and treatment of colorectal cancer in clinic in the future." (PMID 32461933, 2020). "MMP-9 plus another protein as a combination is not a special case in our study; likewise, in colorectal cancer, scMMP-9 plus scRab1B also showed powerful predictive importance for chemotherapy outcomes." (PMID 32377273, 2020). "Moreover, the experiment period was short, so it was difficult to estimate the effects of IL-17, MMP-9 and CD23 on prognosis of colorectal cancer." (PMID 32461933, 2020). "Thus, rHct-S3 decreases the migratory activity of colorectal carcinoma HT-29 cells by the inhibition of MMP-2 and MMP-9 and induces the apoptosis via the activation of caspase-3." (PMID 33348592, 2020).
colorectal cancer (continued). "Matrix metallopeptidase 9 (MMP-9) is unregulated after IRI and promotes micrometastasis of colorectal carcinoma, and may represent a therapeutic target against IRI -induced tumor growth and metastasis." (PMID 31477121, 2019). "In their 32 colorectal cancer patients, MMP-2 and MMP-9 seemed to correlate with more advanced stage; however, by this method, their results may be, at least in part, uncertain." (PMID 29929486, 2018). "Also, it was found that TPS decreased the invading ability of the colorectal cancer cell line CT26, and the MMP-2 and MMP-9 protein expression levels were reduced by TPS treatment." (PMID 29419740, 2018). "Few studies concern the prognostic value of MMP-8, MMP-9, or TIMP-1 in colorectal cancer." (PMID 29929486, 2018). "Although the relevant substrates for MMP-7 and MMP-9 in colorectal cancer progression are currently not known, meta-analyses have shown that high expression of either protease strongly predicts poor overall survival." (PMID 29731961, 2018). "Another study suggested that CTHRC1 upregulated MMP9 via ERK activation in colorectal cancer; however, alteration in MMP9 expression was not indicated in our RNA sequencing data." (PMID 28645305, 2017). "Moreover, CTHRC1 promoted colorectal cancer cell invasiveness through activation of ERK and subsequent induction of MMP9 expression." (PMID 29285247, 2017). "Presented genes, especially ADAM17, MMP9, EphA2, TIMP1, ICAM 11, and CD4, may be used as prognostic markers of advanced stages of colorectal cancer, contributing to the development of new lines of therapy focused on reducing metastasis of the primary tumor." (PMID 27110571, 2016). "MMP-9 has been studied as a prognostic factor for colorectal cancer in T3–T4 node-negative patients; enhanced tumor MMP-9 expression was found to be an independent marker of poor prognosis." (PMID 25888323, 2015). "Here, we report the development of a highly selective and potent allosteric antibody inhibitor of MMP9: we show that inhibition of MMP9 is efficacious in mouse models of UC and colorectal cancer, and that this therapy does not induce MSS in a rat model." (PMID 25961845, 2015). "Recombinant or isolated gelatinase B/MMP-9 hemopexin domain inhibits gelatinase B/MMP-9 activity, hampers colorectal cancer cell adhesion and migration, inhibits gelatinase B/MMP-9-induced functions in chronic lymphocytic Leukemia B cells, and inhibits angiogenesis in glioblastoma xenografts." (PMID 24473089, 2014). "With this data of immune-expression in colorectal cancer tissues, it is very difficult to speculate the close mechanism between CTHRC1 and MMP9." (PMID 24504172, 2014). "The colorectal cancer patients saw similar changes after their tumors were removed with their average VEGF-A plasma levels dropping from 109.6 μg/mL to 57.6 μg/mL and their MMP-9 plasma levels going from 370.1 ng/mL to 190.3 ng/mL." (PMID 20445741, 2010). "The MMP-2 and MMP-9 protein levels in the colorectal cancer homogenates did not correlate with their respective SNP genotypes." (PMID 18506186, 2008). "Also in our present cohort of colorectal carcinoma patients, we found that MMP-2 and MMP-9 levels within the tumours are of significance to survival." (PMID 18506186, 2008). "Therefore, we classified colorectal cancer into colon and rectal cancer and examined differences in the expression of MMP-2, MMP-9, TIMP-1, TIMP-2, uPA, uPAR and PAI-1 between colon and rectal cancer." (PMID 16916471, 2006). "Colorectal cancer is characterized by a significant increase in key areas, including: (i) cancer growth markers, specifically PCNA; (ii) cancer metastasis biomarkers, such as MMP-9 level; (iii) inflammation markers, like IL-6; and (iv) DNA fragmentation as an apoptotic biomarker." (PMID 41307829, 2025).
colorectal cancer (continued). "Similarly, Curcumin treatment of a colorectal cancer cell line has been demonstrated to regulate the NFκβ pathway, suppressing the expression of key regulatory genes involved in cell survival and cell cycles, such as cyclin D1, Bcl-2, VEGF, and MMP9." (PMID 36835252, 2023). "In this study we identified a connection of MED28 with EMT and cell growth in human colorectal cancer cells such that MED28 regulates Wnt/β-catenin signaling and controls transcription factors involved in downregulating E-cadherin and upregulating mesenchymal markers such as MMP9 and fibronectin." (PMID 36072467, 2022). "Also, chrysin and daidzein decreased CXCL1 and MMP-9, essential molecules released by the TME that facilitate tumor progression in the rat model of colorectal cancer; therefore, chrysin and daidzein have potential in preventing colorectal cancer angiogenesis and metastasis." (PMID 34950252, 2021). "The results of this experiment showed that the concentrations of IL-17, MMP-9 and CD23 in peripheral blood of patients with colorectal cancer were significantly increased, suggesting that IL-17, MMP-9 and CD23 might be involved in occurrence and development of colorectal cancer." (PMID 32461933, 2020). "Furthermore, MDSCs may introduce high levels of MMP9 and pro-MMP9 into the extracellular milieu, regulating VEGF bioavailability for colorectal cancer cells." (PMID 32849517, 2020). "The concentrations of IL-17, MMP-9 and CD23 obviously increase in peripheral blood of patients with colorectal cancer, they are negatively correlated with treatment time and are significantly correlated with TNM staging and differentiation degree of colorectal cancer." (PMID 32461933, 2020). "Thus, we detected the expression of MMP9, MMP12, and TWIST1 in colorectal cancer cells." (PMID 26820130, 2016). "Since MMP-9 is closely involved in inflammation as well as in oncologic processes, the MMPI deflamin could possibly be used in both approaches treatments, especially those related to the digestive tract, such as colorectal cancer and inflammable bowel diseases." (PMID 34359533, 2021). "Furthermore, with the increase of pathological grading, the staining intensity of LCN-2 and MMP-9 in neoplastic cells of LSTs gradually increased, and LCN-2 and MMP-9 staining intensity in high-grade intraepithelial LSTs was more intense than in TNM stage I colorectal carcinomas, respectively." (PMID 27339395, 2016). "The specific sites of positive staining for LCN-2 and MMP-9 were cytoplasm in LSTs and TNM stage I colorectal carcinomas, whereas no staining or only faint staining was found in the normal control group." (PMID 27339395, 2016). "On the contrary, there was more evidence indicating that overexpression of MMP9 in cancer cells was not a favorable prognosis factor in non-small cell lung cancer(NSCLC), colorectal cancer, and oesophageal carcinoma, etc." (PMID 20534121, 2010). "At present, the functions of IL-17, MMP-9 and CD23 in colorectal cancer have not been confirmed." (PMID 32461933, 2020). "Many factors and genes may be involved in the occurrence and development of colorectal cancer, but the functions of IL-17, MMP-9 and CD23 in colorectal cancer have not yet been clear." (PMID 32461933, 2020). "However, in the colorectal cancer invasion area, the lack of TIMP-1 (an MMP-9-specific inhibitor) expression may indicate that MMP-9 enzyme activity causes proteolytic degradation of the ECM components without any inhibition or control of connective tissue remodelling." (PMID 39337393, 2024).